GPX4 (glutathione peroxidase 4)
Diseases named in the same sentence as GPX4 in open-access papers (continued):
Sharing a sentence is not in itself a finding about the gene and the disease.
endometrial cancer (16 papers, 2019 to 2026). Primary or metastatic malignant neoplasm involving the endometrium (mucous membrane that lines the endometrial cavity). "This process diminishes the stability of glutathione peroxidase 4 (GPX4) mRNA, heightens lipid peroxidation, and accelerates ferroptosis in endometrial cancer." (PMID 39802639, 2025). "PRMT3 inhibitors, such as SGC707, can restore the normal m6A modification of GPX4 mRNA, reversing cisplatin resistance in endometrial cancer cells." (PMID 39045454, 2024). "For example, the GPX4 inhibitor RSL3 effectively inhibits the proliferation of the medroxyprogesterone acetate (MPA)-resistant endometrial cancer cell line ECC-1 by enhancing oxidative stress and inducing ferroptosis, thereby reversing resistance." (PMID 39045454, 2024). "In conclusion, our results provide new insights into the progress of GPX4 in EC and provide a new theoretical basis for the prevention and treatment of patients with endometrial cancer." (PMID 35962333, 2022). "PTPN18 expression is upregulated in endometrial cancer and inhibited ferroptosis by upregulating the activity of GPX4/xCT, thus promoting the growth of endometrial cancer cells." (PMID 35775079, 2022). "Overall, these results demonstrated that GPX4 expression was elevated in tumor tissues of patients with endometrial cancer." (PMID 35962333, 2022). "In order to verify the effect of GPX4 on endometrial cancer, an EC xenograft tumor model in nude mice was established to evaluate the effect of GPX4 knockdown in vivo." (PMID 35962333, 2022). "In conclusion, our results suggest that GPX4 inhibits ferroptosis and promotes endometrial carcinoma progression through ELK1 transcriptional activation, and ELK1 / GPX4 axis is expected to become a new direction for the treatment of EC." (PMID 35962333, 2022). "We then analyzed the expression of ELK1 and GPX4 in EECs and five different endometrial carcinoma cell lines." (PMID 35962333, 2022). "Therefore, GPX4-suppressed ferroptosis can be an important reason for the initiation of endometrial cancer." (PMID 35847989, 2022). "Taken together, ELK1 could directly activate GPX4 transcription by binding to its promoter region in endometrial carcinoma." (PMID 35962333, 2022). "Mechanistically, silencing of PTPN18 induced ferroptosis in endometrial cancer cells by increasing intracellular reactive oxygen species (ROS) levels and p-p38 expression as well as decreasing the expression of glutathione peroxidase 4 (GPX4) and system xc(-) cystine/glutamate antiporter (xCT)." (PMID 35957898, 2022). "The results of the present study suggest that ELK1 / GPX4 axis plays an important role in the progress of EC by promoting the malignant biological behavior and inducing ferroptosis of EC cells, which provides evidence for investigating the potential therapeutic strategies of endometrial cancer." (PMID 35962333, 2022). "In endometrial cancer, ELK1-mediated GPX4 upregulation drives chemoresistance, highlighting ferroptosis induction as a strategy to overcome treatment failure." (PMID 41824195, 2026). "In endometrial cancer (EC), protein arginine methyltransferase 3 (PRMT3)-mediated METTL14 promotes ferroptosis sensitivity by reducing the expression and stability of glutathione peroxidase 4 (GPX4)." (PMID 40823093, 2025). "In endometrial carcinoma, PRMT3 drives malignant progression by methylating METTL14, reducing m6A modification of GPX4." (PMID 40050608, 2025). "Uniquely, silencing of PTPN18 induced ferroptosis in endometrial cancer cells through p-P38-mediated GPX4/xCT downregulation, while downregulation of PTPN18 can inhibit proliferation and metastasis and promote apoptosis of endometrial cancer." (PMID 35328170, 2022). "In this study, after treatment of AF, the expressions of SLC7A11, GPX4, and FTH1 were upregulated, and the expression of ACSL4 was downregulated, indicating that AF induced the ferroptosis of endometrial carcinoma KLE cells." (PMID 35635082, 2022).
endometrial cancer (continued). "The heatmap in endometrial cancer showed that ELANE and GSDMD were upregulated and GPX4 and TIRAP were downregulated." (PMID 34722500, 2021). "Considering the unique role of ELK1 in activating gene transcription related to cancer progression, we conducted an in-depth evaluation of its value in endometrial carcinoma and confirmed that ELK1 enhanced GPX4 transcription, inhibited ferroptosis, and promoted cancer progression." (PMID 35962333, 2022).
intracerebral hemorrhage (16 papers, 2020 to 2025). A cerebrovascular disorder characterized by bleeding into one or both cerebral hemispheres including the basal ganglia and the cerebral cortex. "Previous research has found that an adaptive response to ferroptosis involving glutathione peroxidase 4 (GPX4) is triggered after intracerebral hemorrhage." (PMID 38386166, 2024). "Dauricine also attenuated secondary brain injury after intracerebral hemorrhage by up-regulating the co-expression of GPX4 and glutathione reductase (GSR) to inhibit neuronal ferroptosis." (PMID 35481263, 2022). "Ferrostatin-1 treatment can significantly increase the protein level of GPX4 in brain tissue after intracerebral hemorrhage and reduce the BBB damage caused by intracerebral hemorrhage." (PMID 35663422, 2022). "Meanwhile, dauricine protects ferroptotic brain damage after intracerebral hemorrhage through upregulating GPX4 and glutathione reductase (GSR)." (PMID 36435804, 2022). "In brain trauma and secondary brain injury after intracerebral hemorrhage, down‐regulation of GPX4 leads to imbalance of the lipid oxidation microenvironment, ultimately inducing ferroptosis of neurons." (PMID 34048148, 2021). "have demonstrated that the content of GPX4 is significantly decreased in the acute phase of intracerebral hemorrhage and that upregulating the expression of GPX4 could save rats." (PMID 37266433, 2023). "However, another study reported increased GPx4 expression 6 h after intracerebral hemorrhage (ICH) induction." (PMID 36184790, 2022). "Oxidative stress damage induced by specific GPX4 deletion in the brain is observed during the acute phase of intracerebral hemorrhage (ICH) and subsequent secondary brain injury (SBI) and finally leads to hemorrhagic stroke which can be relieved by an increasing GPX4 levels." (PMID 35118067, 2021). "In the acute phase of intracerebral hemorrhage, the expression levels of GPX4 in neurons decreased significantly, while the enhancement of its gene expression significantly inhibited the onset of neuronal ferroptosis and improved the prognosis of intracerebral hemorrhage in rats." (PMID 35481263, 2022). "Additionally, GPX4 expression level was significantly reduced during acute intracerebral hemorrhage, and increasing GPX4 expression can ameliorate secondary neuronal death by ferritin, thereby improving the outcome of intracerebral hemorrhage." (PMID 36686700, 2022). "Intracerebral hemorrhage injury can be alleviated by the administration of ferroptosis inhibitors, the mechanism of which is mainly related to iron overload, decreased expression of glutathione peroxidase 4, and increased activity of arachidonic acid-dependent lipoxygenase-5 (ALOX5)." (PMID 34413966, 2021). "Similarly, several studies also reported that HET0016 is a promising ferroptosis inhibitor for intracerebral hemorrhage treatment through decreasing the production of 20-HETE, an accelerator of lipid peroxidation, and increasing GPX4 expression." (PMID 35902564, 2022).
esophageal cancer (15 papers, 2019 to 2025). A primary or metastatic malignant neoplasm involving the esophagus. "We demonstrated that the overexpression of phospho-Hsp27and GPX4 in tumor specimens was associated with a poor prognosis in patients with esophageal cancer." (PMID 35053196, 2021). "Esophageal cancer stem cells displayed strong lipid peroxidation, elevated iron concentration, and high GPX4 expression." (PMID 40969276, 2025). "The highly expressed GPX4 protein suppressed ferroptosis in esophageal cancer stem cells, suggesting chemoradiotherapy resistance." (PMID 40969276, 2025). "Our findings suggested that PKCiota suppressed the ferroptosis of esophageal cancer cells by stopping the USP14-mediated autophagic degradation of GPX4." (PMID 38247539, 2024). "Previous reports have demonstrated that high FSP1 and GPX4 expression is a poor prognostic factor for esophageal cancer." (PMID 39723384, 2024). "Esophageal cancer stem-like cells exhibited higher GPX4 and xCT expression, escaping ferroptosis-induced cell death." (PMID 37433225, 2023). "We further demonstrated that the expression of GPX4 in tumorous specimens from esophageal cancer patients is correlated with a poor prognosis." (PMID 35053196, 2021). "This was the first study to demonstrate the use of GPX4 as a prognostic indicator in esophageal cancer." (PMID 35053196, 2021). "More importantly, we determined that the expression of phospho-Hsp27 and GPX4 in tumorous specimens is predictive of poor prognosis in patients with esophageal cancer." (PMID 35053196, 2021). "Our results also revealed a correlation between phospho-Hsp27 and GPX4 expression levels and poor prognosis in patients with esophageal cancer." (PMID 35053196, 2021). "In esophageal carcinoma (ESCA), GPX4 expression was significantly associated with the infiltration of macrophage and myeloid dendritic cell, and AIFM2 expression was significantly associated with the infiltration of CD4+ T cell." (PMID 34722530, 2021). "Overexpression of GPX4 in oesophageal cancer patients correlates with the upregulation of gene sets involved in protein localisation to the ER and membrane, a process that, if dysregulated, can contribute to carcinogenesis." (PMID 30578123, 2019). "As a result, targeting GPX4 expression may be one of the treatment methods for substantially curing esophageal cancer and improving patients’ prognoses." (PMID 40969276, 2025). "Based on these results and previous experiments, we concluded that overactivated NRF2 may affect the sensitivity of esophageal cancer cells to radiotherapy by regulating the expression of GPX4 through GCLM." (PMID 38340316, 2024). "To investigate the clinical significance of Hsp27and GPX4, we utilized immunohistochemical (IHC) staining to examine the expression of Hsp27 and GPX4 in the tumorous specimens of patients who underwent surgical resection for esophageal cancer in our hospital." (PMID 35053196, 2021). "Finally, we determined that Hsp27 and GPX4 are valuable prognostic indicators in cases of esophageal cancer." (PMID 35053196, 2021). "GPX4 overexpression may represent a novel biomarker and a potential therapeutic target for the treatment of oesophageal cancer." (PMID 30578123, 2019). "Therefore, the regulation of the NRF2/GCLM/GPX4 pathway may provide a new therapeutic strategy for overcoming radiotherapy resistance in esophageal cancer cells." (PMID 40707557, 2025). "In our previous experiments, we verified at the cellular level that NRF2 affects GPX4 expression by regulating the expression of GCLM, thereby influencing the resistance of esophageal cancer cells to radiotherapy." (PMID 40707557, 2025). "The TIMER 2.0 database displayed that the expression of GPX4 was substantially upregulated in Bladder Urothelial Carcinoma, Breast invasive carcinoma, COAD, Esophageal Carcinoma, etc.." (PMID 40746894, 2025).
esophageal cancer (continued). "PKCiota was negatively regulated by miR-145-5p, which decreased in esophageal cancer, and also regulated by USP14 and GPX4 by a positive feedback loop." (PMID 38247539, 2024). "Moreover, simultaneous regulation of GPX4 and FSP1 reportedly induces ferroptosis in esophageal cancer cell lines." (PMID 39723384, 2024). "CircPVT1 sponge miR-30a-5p targets and binds frizzled class receptor 3 (FZD3), affects the expression levels of p-β-catenin, GPX4 and SLC7A11, inhibits cellular ferroptosis, affects esophageal cancer 5-FU chemotherapy sensitivity and promotes the development of esophageal cancer." (PMID 37152286, 2023).
liver diseases (15 papers, 2021 to 2026). "The study also provides a foundation for exploring GPX4 as a therapeutic target in liver diseases characterized by oxidative and ER stress." (PMID 40051561, 2025). "In liver diseases, Nrf2 and GPX4 are widely studied for their roles in OS response." (PMID 41258710, 2026). "Of course, GPX4 is also involved in the occurrence and development of some liver diseases." (PMID 38515187, 2024). "Notably, GPX4 also plays a crucial role in the occurrence and progression of liver diseases." (PMID 39119475, 2024). "Targeting GPX4 may become a new way to treat a variety of liver diseases." (PMID 38515187, 2024). "Therefore, although further investigations are required, this study suggests that NeuroD1/GPX4 regulation may also be involved in other liver diseases." (PMID 38134213, 2023). "Therefore, targeting GPX4 may be a potential therapeutic approach for a variety of liver diseases." (PMID 39119475, 2024). "Extensive studies have shown that GPX4 is involved in the occurrence and development of a variety of inflammatory diseases and liver diseases, but the potential significance and prognostic value of GPX4 in HBV-ACLF patients have not been determined." (PMID 39119475, 2024). "For non-cancer liver diseases, we aim to protect live cells from cell death, lipid peroxidation, and ROS release; induction of GPX4 expression was reported to be helpful to inhibit ferroptosis." (PMID 34820376, 2021).
pancreatic ductal adenocarcinoma (15 papers, 2020 to 2025). An infiltrating adenocarcinoma that arises from the epithelial cells of the pancreas. "GSH also acts as an essential cofactor for GPX4, in Pancreatic ductal adenocarcinoma (PDAC) cells, Cu binds to GPX4 and facilitates its autophagic degradation, thereby inducing ferroptosis." (PMID 41158661, 2025). "Activating transcription factor 4 mediates heat shock protein family A (Hsp70) member 5 expression, which in turn binds to GPX4 resulting in increased GPX4 protein stability with unclear mechanism in pancreatic ductal adenocarcinoma cells." (PMID 36289191, 2022). "This study focused on improving the gemcitabine sensitivity in pancreatic ductal adenocarcinoma (PDAC) by targeting ATF4/HSPA5/GPX4 axis, while the exact molecular mechanism was not deeply studied." (PMID 40603306, 2025).
acute myeloid leukemia (14 papers, 2021 to 2026). Acute myeloid leukemia (AML) is a group of neoplasms arising from precursor cells committed to the myeloid cell-line differentiation. "It was found that ferroptosis induced by 50 μM SFN in acute myeloid leukemia cells were accompanied by decreased Glutathione Peroxidase 4 (GPX4) expression and increased lipid peroxidation, which provided a new extension of SFN potential as an anticancer agent." (PMID 38902597, 2024). "For example, glutathione peroxidase 4 (GPX4) was overexpressed in various hematologic malignancies, including acute myeloid leukemia (AML), where GPX family members were upregulated under oxidative stress and correlated with clinical prognosis." (PMID 41457818, 2026). "Although acute myeloid leukemia (AML) cells, especially relapsed and refractory (R/R)-AML, present high GPX4 levels and enzyme activities, pharmacological inhibition of GPX4 alone has limited application in AML." (PMID 38378601, 2024). "In addition, GPX4 is highly expressed in most of acute myeloid leukemia (AML) subtypes compared to normal hematopoietic stem cells." (PMID 38977956, 2024). "And high expression of SLC7A11, GPX4, and AIFM2 were significantly correlated with the shortened OS of acute myeloid leukemia (LAML) patients." (PMID 34722530, 2021). "And high expression of SLC7A11, GPX4, and AIFM2 were significantly correlated with the shortened OS of acute myeloid leukemia patients." (PMID 34722530, 2021). "In acute myeloid leukemia, It has been shown REV increased the expression of hsa-miR-335-5p while decreased the expression of NFS1 and GPX4; it increased ferroptosis in AML cells through the Hsa-miR-335-5p/NFS1/GPX4 pathway in a manner dependent on ROS." (PMID 40552277, 2025). "Similarly, neratinib induces ferroptosis in acute myeloid leukemia (AML) cells, which is characterized by increased ROS and malondialdehyde content, enhanced Fe2+ activity, and downregulated GPX4 and ferritin heavy chain 1 expression." (PMID 38982494, 2024). "Acute myeloid leukemia (AML) displays an opposite ferroptotic phenotype compared with ALL, with both GPX4 and FSP1 highly expressed in AML tumor tissues." (PMID 40862825, 2025). "However, a comprehensive understanding of the roles of GPX4 and AIFM2 in acute myeloid leukemia (AML) has not yet been achieved." (PMID 38032290, 2023).